TRAF3IP2 (TRAF3 interacting protein 2)
Description:
E3 ubiquitin ligase that catalyzes 'Lys-63'-linked polyubiquitination of target protein, enhancing protein-protein interaction and cell signaling. Transfers ubiquitin from E2 ubiquitin-conjugating enzyme UBE2V1-UBE2N to substrate protein. Essential adapter molecule in IL17A-mediated signaling. Upon IL17A stimulation, interacts with IL17RA and IL17RC receptor chains through SEFIR domains and catalyzes 'Lys-63'-linked polyubiquitination of TRAF6, leading to TRAF6-mediated activation of NF-kappa-B and MAPkinase pathways.
Synonyms: ACT1; C6orf2; C6orf4; C6orf5; C6orf6; DKFZP586G0522; CIKS; CANDF8; PSORS13
Tractability: Small molecule: a drug acting on it is in phase 2 or 3 trials.
Target class: Enzyme; Transferase
Safety:
Unwanted effects reported when the protein is acted on. In parentheses: how it was acted on, where the effect was seen, and who reports it.
Steven-Johnson Syndrome (SJS) and Toxic Epidermal Necrolysis (TEN) (source: ClinPGx)
Gene: Protein-coding gene on chromosome 6 (111,555,381 to 111,606,910, reverse strand). Ensembl gene ENSG00000056972.
Subcellular location (Human Protein Atlas): Golgi apparatus; Vesicles
Gene Ontology:
Molecular function: protein binding; ubiquitin protein ligase activity; signaling receptor binding
Biological process: inflammatory response; interleukin-17-mediated signaling pathway; interleukin-17A-mediated signaling pathway; positive regulation of canonical NF-kappaB signal transduction; positive regulation of defense response to virus by host; protein K63-linked ubiquitination; humoral immune response; intracellular signal transduction; positive regulation of interleukin-13 production; positive regulation of interleukin-5 production; regulation of cell growth; regulation of keratinocyte proliferation; T-helper 17 type immune response; B cell affinity maturation; B cell homeostasis; B cell mediated immunity; CD40 signaling pathway; cellular response to cytokine stimulus; cellular response to interleukin-17; cytokine-mediated signaling pathway; eosinophil homeostasis; eosinophil mediated immunity; establishment of T cell polarity; gene expression; heart development; and 20 more
Cellular component: cytoplasm; extrinsic component of cytoplasmic side of plasma membrane; plasma membrane; cytoplasmic vesicle; nucleus
Genetic constraint (gnomAD): Loss-of-function variants: 29 observed, 51.28 expected, observed/expected ratio (o/e) 0.57, 90% interval 0.42 to 0.77. The upper end of that interval is the gene's LOEUF score, 0.77, which puts it in group 3 of 6, group 1 being the genes least tolerant of losing a copy. Missense variants: 531 observed, 684.57 expected, observed/expected ratio (o/e) 0.78, 90% interval 0.72 to 0.83. Synonymous variants: 238 observed, 261.98 expected, observed/expected ratio (o/e) 0.91, 90% interval 0.82 to 1.01.
Homologues: Orthologues: chimpanzee TRAF3IP2 (99% identical), macaque TRAF3IP2 (95% identical), pig TRAF3IP2 (85% identical), guinea pig TRAF3IP2 (82% identical), dog TRAF3IP2 (81% identical), mouse Traf3ip2 (80% identical), rat Traf3ip2 (78% identical), rabbit TRAF3IP2 (74% identical).
Diseases named in the same sentence as TRAF3IP2 in open-access papers:
TRAF3IP2 is named in the same sentence as 111 diseases in open-access papers, as found by Europe PMC text mining. Sharing a sentence is not in itself a finding about the gene and the disease. The quoted sentences say what the papers report.
psoriasis (51 papers, 2011 to 2025). An autoimmune condition characterized by red, well-delineated plaques with silvery scales that are usually on the extensor surfaces and scalp. "This suggests that both coding and gene regulation of TRAF3IP2 contribute to psoriasis susceptibility at this locus." (PMID 40021644, 2025). "A psoriasis risk variant in the TRAF3 interacting protein 2 (TRAF3IP2) gene has been shown to induce Th17 differentiation and IL17A secretion, which is potentiated in the presence of NETs." (PMID 37628670, 2023). "We found variants already associated directly to psoriasis in the TRAF3IP2 gene, and interestingly we found a missense variant in the NAT9 gene." (PMID 36902182, 2023). "This process was also controlled by the variant of the TRAF3IP2 gene, which is associated with increased risk of psoriasis." (PMID 35163760, 2022). "TRAF3 interacting protein 2 (TRAF3IP2) is another psoriasis susceptibility gene associated with keratinocytes." (PMID 35075118, 2022). "Feeding a diet rich in fucoidan (a seaweed fiber) in the psoriasis mice model, induced by a Traf3ip2 mutation, ameliorated symptoms of psoriasis-like dermatitis with increasing Bacteroides in the gut." (PMID 34501328, 2021). "Humans with the loss of function allele of the IL-17R signaling component ACT1 (TRAF3IP2) are more susceptible to psoriasis, but Act1-deficient mice are afflicted with spontaneous skin inflammatory diseases." (PMID 32065580, 2020). "In the murine imiquimod-induced psoriasis model, topical imiquimod induces epidermal thickening that is significantly alleviated in Traf3ip2 (Act1)-deficient mice in which IL-17 signaling is blocked." (PMID 32070069, 2020). "Of note, the gene encoding ACT1 TNF receptor-associated factor 3 interacting protein 2 (TRAF3IP2) is one of the genes with common variants that are highly associated with the susceptibility to psoriasis and psoriatic arthritis." (PMID 32010143, 2019). "Another locus of particular interest was rs33980500 [OMIM: 614070] in the TRAF3IP2 gene as it has been identified as a risk factor for Psoriasis, a skin related condition." (PMID 31604968, 2019). "Th17 induction was enhanced by a psoriasis risk-associated variant in the TRAF3IP2 gene encoding the D10N variant of Act1 which serves as a key mediator of IL-17 signal transduction." (PMID 31649677, 2019). "TNF receptor-associated factor 3 Interacting Protein 2 (TRAF3IP2) has been described as a genetic susceptibility locus for psoriasis and appears to facilitate IL-17 signaling in both psoriasis and systemic lupus erythematosus." (PMID 31402919, 2019). "In fact, TRAF3IP2 resides in a known susceptibility locus for inflammatory diseases such as psoriasis and psoriatic arthritis, Crohn’s disease, and type I diabetes." (PMID 30038719, 2018). "Additional genetic associations with the development of RA have been suggested for PSORS1C1/CDSN and TRAF3 Interacting Protein 2 (TRAF3IP2) genes that are well-known susceptibility genes for psoriasis and psoriatic arthritis." (PMID 28107378, 2017). "In the last years TRAF3IP2 gene variants had been described as associated with susceptibility to several diseases such as psoriasis and psoriatic arthritis." (PMID 25775161, 2015). "Of note, the genetic variation of the Act1 gene (TRAF3IP2), which is the key adaptor to propagate IL-17-mediated downstream signaling, is associated with susceptibility to psoriasis and psoriatic arthritis by genome-wide association studies (GWAS)." (PMID 26146463, 2015). "Comparing 517 cases against 517 controls, we found significant association (both by allele and by genotype) of TRAF3IP2_rs33980500 with increased psoriasis risk." (PMID 24005976, 2014). "We have replicated the association of TRAF3IP2-_rs33980500 variant with the susceptibility to psoriasis." (PMID 24005976, 2014).
psoriasis (continued). "Mutations of the TRAF3IP2 gene have been associated with susceptibility to several autoimmune diseases, such as psoriasis, psoriatic arthritis, chronic plaque psoriasis, inflammatory bowel disease and type 1 diabetes." (PMID 24416204, 2014). "Functional experimental work is needed to characterize the role of hsa-mir-1279 in the regulation of these genes in-depth, in particular TRAF3IP2 as this gene was identified in two independent GWAS as a susceptibility locus for psoriasis." (PMID 23029284, 2012). "One new PsA and psoriasis-susceptibility gene, TRAF3IP2, codes for the adaptor protein ACT1 (nuclear factor-κB activator 1), a regulator of the NF-κB pathway involved in IL-17 signaling." (PMID 22513239, 2012). "Among them, TRAF3IP2 was shown to be the most reproducibly associated locus and showed a psoriasis odds ratio of 1.70." (PMID 21559375, 2011). "Feeding with diet rich in fucoidan, seaweed fiber, in psoriasis model mice induced by Traf3ip2 mutation, ameliorated symptoms of psoriasis-like dermatitis, scratching behaviors, and increased the secretion of mucin in ileum and of IgA in cecum, with alteration of the composition of gut microbiota." (PMID 32751360, 2020). "In addition, TRAF3IP2 has been identified as a susceptibility locus in European and Japanese populations for both psoriasis and psoriatic arthritis." (PMID 31130981, 2019). "In another GWAS, rs240993 (TRAF3IP2 gene) was associated with psoriasis in Caucasian patients." (PMID 24069534, 2013). "For example, an isoform of TRAF3IP2 with a mutation may cause the formation of psoriasis." (PMID 29515135, 2018). "Genetic research showed the key role of the TRAF3IP2 gene as the basis for the increased expression of IL-17 in psoriasis." (PMID 35163760, 2022). "Psoriasis susceptibility genes have been identified as tyrosine kinase 2 (TYK2) and TRAF3-interacting protein 2 (TRAF3IP2)." (PMID 35409152, 2022). "The present study demonstrated that fucoidan affects psoriasis symptoms; it ameliorated the effect of phenotype and altered the intestinal microbiota and the quality of secreted IgA and mucin in m-Traf3ip2 mutant mice." (PMID 32164223, 2020). "Consistently, many psoriasis susceptibility genes encode the TRAF6 signaling players, such as ACT1 (TRAF3IP2), A20 (TNFAIP3), ABIN1 (TNIP1), IL-36Ra (IL36RN), IkappaBzeta (NFKBIZ), and CARD14." (PMID 31156649, 2019). "Another important genetic association to psoriasis is the gene TRAF3IP2, which encodes the protein Act1, which is part of the signal cascade of IL-17." (PMID 29963046, 2018). "Increasing evidence indicates that genetic mutations in genes such as TNFAIP3, TNIP1, NFKBIA, TRAF3IP2, and CARD14 result in an impaired negative regulation of NF‐κB proinflammatory activity leading to psoriasis." (PMID 28377495, 2017). "For some loci, this is a stronger effect size (TRAF3IP2, REL, FBXL19); for others, different genetic variants at the same locus predispose to psoriasis and PsA (IL23R) whereas other loci appear specifically associated with PsA (HLA B27, 5q31 locus)." (PMID 26255310, 2016). "These sub-groups correlated with the composition of the inflammatory infiltrate, but were only weakly associated with increased risk allele frequency at some psoriasis susceptibility loci (e.g., REL, TRAF3IP2 and NOS2)." (PMID 22479649, 2012). "Many psoriasis risk genes are involved in this pathway; TNFAIP3, NF-ΚBIZ and TNIP1 are involved in pathway regulation, with NF-ΚBIA inhibiting the pathway, RELA coding for an NF-κB subunit and TRAF3IP2 coding for ACT1." (PMID 38785955, 2024). "Recently, an important genetic influence of the polymorphism in TRAF3IP2 on the susceptibility to psoriasis, but not to atopic dermatitis, was reported in a Japanese population." (PMID 32164223, 2020).
psoriasis (continued). "There are no risk alleles in IL17A, but psoriasis-associated SNPs have been identified in TRAF3IP2, which encodes an IL-17 receptor adaptor while SNPs in IL23A, which encodes p19, are associated with psoriasis susceptibility." (PMID 31130981, 2019). "The TRAF3IP2 gene is an essential adaptor in the IL-17 signaling pathway contributing to psoriasis." (PMID 29515135, 2018). "Functional studies suggest TRAF3IP2 gene as important factor in psoriasis development." (PMID 24005976, 2014). "The polymorphisms we used were based on earlier reports showing significant associations with RA, psoriatic arthritis, psoriasis and Inflammatory Bowel Disease and included three SNPs (rs6540679, rs12569232, rs10863888) of TRAF5 and three SNPs (rs13210247, rs33980500, rs13190932) of TRAF3IP2." (PMID 24416204, 2014). "Seven of these have previously been reported for psoriasis (MHC, TRAF3IP2, IL12B, IL23R, IL23A-STAT2, TNIP1, TYK2)." (PMID 25651891, 2015). "The protein product of TRAF3IP2 gene, Act 1, binds with interleukin 17 receptor and is essential for IL17-dependent signaling in autoimmune and inflammatory disease, including psoriasis." (PMID 24005976, 2014).
psoriatic arthritis (11 papers, 2012 to 2022). Joint inflammation associated with psoriasis. "In recent genome-wide association studies for psoriatic arthritis (PsA) and psoriasis vulgaris, common coding variants in the TRAF3IP2 gene were identified to contribute to susceptibility to both disease entities." (PMID 22513239, 2012). "Other polymorphisms of the IL-23/IL-17A axis, such as SNPs in TRAF3IP2 that code for the adaptor Act1, a downstream target of IL-17R, which confers susceptibility to psoriatic arthritis, may be evaluated in AS." (PMID 27415816, 2016).
autoimmune disease (9 papers, 2011 to 2025). A disorder resulting from loss of function or tissue destruction of an organ or multiple organs, arising from humoral or cellular immune responses of the individual to their own tissue constituents. "TRAF5 and TRAF3IP2 have been reported to be associated with several autoimmune diseases." (PMID 24416204, 2014). "Consistently, TRAF3IP2 is recognized to play critical roles in the pathogenesis and progression of various autoimmune diseases." (PMID 36046049, 2022). "Given that OMAS is an autoimmune disorder, TRAF3IP2 overexpression may play a key role in the immune and inflammatory response in OMAS." (PMID 41189279, 2025).
breast cancer (9 papers, 2015 to 2025). A primary or metastatic malignant neoplasm involving the breast. "Our analysis of Breast Cancer Gene-Expression Miner data indicates that higher TRAF3IP2 expression is significantly associated with worse DFS, DMFS, and OS in basal-like TNBC." (PMID 41436543, 2025). "Both Rab27a and TRAF3IP2 play a causal role in breast cancer growth and metastasis." (PMID 32483202, 2020). "By demonstrating a strong correlation between TRAF3IP2 expression and poorer clinical outcomes, we highlight the possibility that TRAF3IP2 contributes to both the aggressive phenotype and reduced survival rates characteristic of this breast cancer subtype." (PMID 41436543, 2025). "A limitation of the present study is that we used a single breast cancer cell line to investigate potential roles of silencing Rab27a and TRAF3IP2 on tumor growth." (PMID 32483202, 2020). "Together, these novel data suggest that TRAF3IP2 is a potent pro-tumorigenic mediator, and thus a potential target in breast cancer." (PMID 32483202, 2020). "Here we investigated the roles of Rab27a, a player in exosome release, and TRAF3IP2, an inflammatory mediator, in development and metastasis of breast cancer (BC) in vivo." (PMID 32483202, 2020). "Recent studies have revealed that TRAF3IP2 promotes glioblastoma growth by enhancing inflammation of the microenvironment and that the silence of TRAF3IP2 inhibits the metastasis and development of breast cancer." (PMID 35897085, 2022). "The role of Rab27a and TRAF3IP2 in many tumors, including breast cancer, is still unclear." (PMID 32483202, 2020). "Interestingly in the present study, silencing Rab27a or TRAF3IP2 in the breast cancer cell line MDA-MB231 differentially regulated the expression of genes involved in tumor development, growth and metastasis." (PMID 32483202, 2020). "The results show that silencing Rab27a or TRAF3IP2 in the triple negative breast cancer (BC) cell line MDA-MB231 results in the formation of a significantly smaller tumor in a breast xenograft model and significantly extends survival." (PMID 32483202, 2020). "To further investigate the clinical relevance of TRAF3IP2 in TNBC, we examined publicly available data from Breast Cancer Gene-Expression Miner v5.2 (bc-GenExMiner v5.2), focusing on basal-like (PAM50) breast cancer cases." (PMID 41436543, 2025). "TRAF3 interacting protein 2 (TRAF3IP2) is an adaptor protein regulating NF-κB signaling downstream of the IL-17 pathway and is known to promote proinflammatory and proangiogenic signaling in glioblastoma and breast cancer." (PMID 41373721, 2025). "Furthermore, the breast cancer cells can induce the expression of Rab27a or TRAF3IP2 in non-malignant breast epithelial 184A1 cells and naïve MSCs via a paracrine mechanism, and demonstrates the impact of breast cancer cells on surrounding non-malignant stroma." (PMID 32483202, 2020).
chronic mucocutaneous candidiasis (8 papers, 2015 to 2023). "Thus, patients with autosomal recessive complete deficiencies in IL-17RA, IL17RC, or ACT1/TRAF3IP2 develop fully penetrant, severe, treatment-refractory mucosal infections by Candida species, termed chronic mucocutaneous candidiasis (CMC)." (PMID 34964702, 2022).